SERPINB11 (serpin family B member 11)
Description:
Has no serine protease inhibitory activity, probably due to variants in the scaffold impairing conformational change.
Synonyms: EPIPIN; SERPIN11
Tractability: PROTAC: ubiquitination databases record sites on it.
Gene: Protein-coding gene on chromosome 18 (63,647,579 to 63,726,432, forward strand). Ensembl gene ENSG00000206072.
Subcellular location: Cytoplasm
Gene Ontology:
Molecular function: serine-type endopeptidase inhibitor activity
Cellular component: cytoplasm
Genetic constraint (gnomAD): Loss-of-function variants: 18 observed, 21.61 expected, observed/expected ratio (o/e) 0.83, 90% interval 0.57 to 1.24. The upper end of that interval is the gene's LOEUF score, 1.24, which puts it in group 5 of 6, group 1 being the genes least tolerant of losing a copy. Missense variants: 397 observed, 354.74 expected, observed/expected ratio (o/e) 1.12, 90% interval 1.03 to 1.22. Synonymous variants: 133 observed, 131.3 expected, observed/expected ratio (o/e) 1.01, 90% interval 0.88 to 1.17.
Homologues: Orthologues: chimpanzee SERPINB11 (97% identical), macaque SERPINB11 (96% identical), dog SERPINB11 (82% identical), pig SERPINB11 (80% identical), rabbit SERPINB11 (78% identical), rat Serpinb11 (68% identical), mouse Serpinb11 (67% identical), tropical clawed frog serpinb11 (43% identical), guinea pig Serpinb11 (32% identical). Paralogues in human: SERPINB1 (45% identical), SERPINB4 (44% identical), SERPINB12 (44% identical), SERPINB3 (43% identical), SERPINB13 (42% identical), SERPINB10 (42% identical), SERPINB8 (42% identical), SERPINB6 (42% identical), SERPINB7 (42% identical), SERPINB9 (42% identical), SERPINB2 (40% identical), SERPINC1 (36% identical), and 24 more.
Diseases named in the same sentence as SERPINB11 in open-access papers:
SERPINB11 is named in the same sentence as 10 diseases in open-access papers, as found by Europe PMC text mining. Sharing a sentence is not in itself a finding about the gene and the disease. The quoted sentences say what the papers report.
ovarian carcinoma (4 papers, 2012 to 2024). A malignant neoplasm originating from the surface ovarian epithelium. "Collectively, we proposed that SERPINB11 deficiency with eupatilin enhances therapeutic applications for epithelial ovarian cancer." (PMID 32503295, 2020). "Particularly, Serpinb11 has been studied primarily in ovarian cancers; however, this is the first study to examine the role of Serpinb11 in GBM." (PMID 38539447, 2024). "Altogether, our results provide the first pre-clinical evidence for the anticancer potential of eupatilin by targeting SERPINB11 in ovarian cancer." (PMID 32503295, 2020). "Eupatilin induced calcium-dependent apoptotic cell death associated with disruption of the endoplasmic reticulum (ER) and mitochondrial axis by targeting SERPINB11 in ovarian cancer cell lines." (PMID 32503295, 2020). "In conclusion, we elucidated the anticancer activities exhibited by eupatilin, which induced calcium-dependent apoptotic cell death associated with disruption of the ER and mitochondrial axis by targeting SERPINB11 in ovarian cancer cells." (PMID 32503295, 2020). "We first demonstrated the anticancer potential of eupatilin, which induced calcium-dependent apoptosis associated with disruption of the ER–mitochondrial axis by targeting SERPINB11 in ovarian cancer cell lines." (PMID 32503295, 2020). "We first demonstrated the anticancer potential of eupatilin as a candidate therapeutic agent targeting SERPINB11 in ovarian cancer cells." (PMID 32503295, 2020). "To validate SERPINB11 as an appropriate anticancer target, we next analyzed the effect of SERPINB11 knockdown on the expression of genes known to promote ovarian cancer." (PMID 32503295, 2020). "We previously reported expression of cysteine protease cathepin B (CTSB), serpin peptidase inhibitor, clade B, member 11 (SERPINB11) and alpha 2 macroglobulin (A2M) in ovarian tissue from hens with ovarian cancer." (PMID 22496782, 2012). "However, there is no clear evidence of the anticancer activities exhibited by the regulation mechanism of SERPINB11 in ovarian cancer." (PMID 32503295, 2020). "Eupatilin-reduced SERPINB11 was completely blocked by SB203580 in both ovarian cancer cells." (PMID 32503295, 2020). "Additionally, eupatilin-reduced SERPINB11 expression enhanced the effect of conventional chemotherapeutic agents against ovarian cancer cell progression." (PMID 32503295, 2020). "Among the members of SERPIN family, the expression of SERPINB11 was found to be high in ovarian endometrial cancer in chickens, but its role in human ovarian cancer cells is not known yet." (PMID 32503295, 2020). "Indeed, CTSB, SERPINB11, A2M, and PTN are genes that we reported to be most abundant in the GE of ovarian cancers in laying hens." (PMID 23843947, 2013).
endometrioid adenocarcinoma of the ovary (1 paper, 2014). "In addition, SERPINB11 expression is dramatically increased in laying hens with progressive endometrioid adenocarcinoma of the ovary." (PMID 25020046, 2014).
inflammatory skin disorders (1 paper, 2021). "In parallel, SERPINB11 and SERPINB13 are human-specifically downregulated, while kallikrein 14, a major player in wound healing and inflammatory skin disorders, is upregulated more than 100 fold." (PMID 35154781, 2021).
tumor (3 papers, 2014 to 2020). "In addition, eupatilin has been shown to reduce tumor formation through a complete reduction of SERPINB11 in adhesion-independent cancer cell growth." (PMID 32503295, 2020).
cancer (2 papers, 2020 to 2025). A tumor composed of atypical neoplastic, often pleomorphic cells that invade other tissues. "Although the role of SERPINB11 is still now largely unclear, there is some evidence that this molecule is increased in several types of cancer, correlating with poor patient prognosis and therapy response." (PMID 40243422, 2025). "Collectively, downregulating SERPINB11 with eupatilin against cancer progression may improve therapeutic activity." (PMID 32503295, 2020).
infectious disease (2 papers, 2012 to 2014). A disorder directly resulting from the presence and activity of a microbial, viral, or parasitic agent in humans. "fourth, the significant association between the pastoral subsistence variable and a trend towards higher frequencies of SERPINB11 alleles (E90 and T181), as if they confer an advantage in environments with higher risk of infectious diseases transmission from domesticated animals to humans." (PMID 22393410, 2012).
adenocarcinoma (1 paper, 2012). A common cancer characterized by the presence of malignant glandular cells. "Indeed, we found that cathepin B (CTSB), serpin peptidase inhibitor, clade B, member 11 (SERPINB11) and alpha 2 macroglobulin (A2M) genes are most abundant in GE of chicken adenocarcinoma." (PMID 22496782, 2012).
SERPINB11 also shares sentences with these, for which no sentence is quoted: clear cell carcinomas (1 paper); endometrioid carcinoma (1); ovarian adenocarcinoma (1).